PLA2G15 (phospholipase A2 group XV)
Description:
Has dual calcium-independent phospholipase and O-acyltransferase activities with a potential role in glycerophospholipid homeostasis and remodeling of acyl groups of lipophilic alcohols present in acidic cellular compartments. Catalyzes hydrolysis of the ester bond of the fatty acyl group attached at sn-1 or sn-2 position of phospholipids (phospholipase A1 or A2 activity) and transfer it to the hydroxyl group at the first carbon of lipophilic alcohols (O-acyltransferase activity). Among preferred fatty acyl donors are phosphatidylcholines, phosphatidylethanolamines, phosphatidylglycerols and phosphatidylserines. Favors sn-2 over sn-1 deacylation of unsaturated fatty acyl groups of phosphatidylcholines, phosphatidylethanolamines, and phosphatidylglycerols. Among preferred fatty acyl acceptors are natural lipophilic alcohols including short-chain ceramide N-acetyl-sphingosine (C2 ceramide), alkylacylglycerols, monoacylglycerols, and acylethanolamides such as anandamide and oleoylethanolamide. Selectively hydrolyzes the sn-1 fatty acyl group of truncated oxidized phospholipids and may play a role in detoxification of reactive oxidized phospholipids during oxidative stress. Required for normal phospholipid degradation in alveolar macrophages with potential implications in the clearance of pulmonary surfactant, which is mainly composed of dipalmitoylphosphatidylcholine (1,2-dihexadecanoyl-sn-glycero-3-phosphocholine) (By similarity). Involved in the first step of bis(monoacylglycero)phosphate (BMP) de novo synthesis from phosphatidylglycerol (1,2-diacyl-sn-glycero-3-phospho-(1'-sn-glycerol), PG). BMP is an important player in cargo sorting and degradation, regulation of cellular cholesterol levels and intercellular communication. At neutral pH, hydrolyzes the sn-1 fatty acyl group of the lysophosphatidylcholines.
Synonyms: ACS; LLPL; LPLA2; LYPLA3; GXVPLA2
Tractability: Small molecule: a structure with a bound ligand is known. Antibody: UniProt places it where antibodies can reach, with high confidence; its Gene Ontology location is reachable by antibodies, with high confidence; UniProt predicts a signal peptide or a membrane-spanning region. PROTAC: ubiquitination databases record sites on it; its protein half-life has been measured.
Target class: Enzyme
Gene: Protein-coding gene on chromosome 16 (68,245,304 to 68,261,063, forward strand). Ensembl gene ENSG00000103066.
Subcellular location: Lysosome; Secreted; Membrane
Subcellular location (Human Protein Atlas): Nucleoplasm; Vesicles
Pathways (Reactome):
Metabolism: Hydrolysis of LPC
Gene Ontology:
Molecular function: acyltransferase activity, transferring groups other than amino-acyl groups; phospholipase A1 activity; phospholipase A2 activity; protein binding; zinc ion binding; acylglycerol O-acyltransferase activity; phosphatidylcholine lysophospholipase activity; phospholipid binding
Biological process: ceramide metabolic process; glycerophospholipid metabolic process; phosphatidylcholine metabolic process; phosphatidylglycerol metabolic process; phosphatidylserine metabolic process; diacylglycerol biosynthetic process; fatty acid catabolic process; phosphatidylcholine catabolic process; phosphatidylethanolamine catabolic process; phospholipid metabolic process; lipid metabolic process
Cellular component: extracellular exosome; extracellular region; lysosome; membrane
Genetic constraint (gnomAD): Loss-of-function variants: 19 observed, 36.41 expected, observed/expected ratio (o/e) 0.52, 90% interval 0.36 to 0.77. The upper end of that interval is the gene's LOEUF score, 0.77, which puts it in group 3 of 6, group 1 being the genes least tolerant of losing a copy. Missense variants: 462 observed, 541.38 expected, observed/expected ratio (o/e) 0.85, 90% interval 0.79 to 0.92. Synonymous variants: 221 observed, 231.31 expected, observed/expected ratio (o/e) 0.96, 90% interval 0.86 to 1.07.
Homologues: Orthologues: chimpanzee PLA2G15 (99% identical), macaque PLA2G15 (99% identical), dog PLA2G15 (90% identical), rabbit PLA2G15 (90% identical), pig PLA2G15 (89% identical), mouse Pla2g15 (88% identical), rat Pla2g15 (88% identical), guinea pig PLA2G15 (87% identical), tropical clawed frog pla2g15 (69% identical), zebrafish pla2g15 (66% identical), Caenorhabditis elegans plag-15 (43% identical), Drosophila melanogaster CG31683 (37% identical), and 1 more. Paralogues in human: LCAT (48% identical).
Diseases named in the same sentence as PLA2G15 in open-access papers:
PLA2G15 is named in the same sentence as 25 diseases in open-access papers, as found by Europe PMC text mining. Sharing a sentence is not in itself a finding about the gene and the disease. The quoted sentences say what the papers report.
phospholipidosis (9 papers, 2012 to 2024). "We previously reported the discovery and characterization of a lysosome-specific phospholipase A2 (PLA2G15) and later reported that amiodarone, a known cause of drug-induced phospholipidosis, inhibits this enzyme." (PMID 34087196, 2021). "Here, we assayed a library of 163 drugs for inhibition of PLA2G15 to determine whether this phospholipase was the cellular target for therapeutics other than amiodarone that cause phospholipidosis." (PMID 34087196, 2021). "For example, PLA2G15 (phospholipase A2 group XV) can act as a ‘positive regulator of immune response’ in the inflammatory response in severe phospholipidosis." (PMID 32883995, 2020). "Because many drugs that cause phospholipidosis inhibit lysosomal phospholipase A2 (LPLA2, PLA2G15, LYPLA3) activity, we investigated whether this enzyme has a role in BMPcatabolism." (PMID 38857781, 2024). "Thirty-six compounds not previously reported to cause phospholipidosis inhibited PLA2G15 with IC50 values less than 1 mM and were confirmed to cause phospholipidosis in an in vitro assay." (PMID 34087196, 2021).
atherosclerosis (2 papers, 2023 to 2025). A disease characterized by the build-up of fatty material and calcium deposition in the arterial wall resulting in partial or complete occlusion of the arterial lumen. "A prior Pla2g15−/− knockout study also reported its presence in foam cells within atherosclerotic lesions in apoE−/− mice, suggesting a role in atherosclerosis." (PMID 40689090, 2025).
dyslipidaemia (1 paper, 2025). "Our study confirmed key proteins (PCSK9, ANGPTL3, LPA), identified potential novel targets (GSTA1, GSTA3, EPPK1, PECR, and PLA2G15), and strengthened evidence for CELSR2 and GAS6 in dyslipidaemia." (PMID 40689090, 2025).
endometriosis (1 paper, 2025). The growth of functional endometrial tissue in anatomic sites outside the uterine body. "There has been limited research on the roles of ACSL5, PLA2G4A, EHHADH, GPAM, PLA2G15, SULT2A1, and ACSL3 in endometriosis, highlighting the necessity for further investigation to elucidate their contributions to its pathogenesis." (PMID 40527850, 2025).
leukemia (1 paper, 2023). A malignant (clonal) hematologic disorder, involving hematopoietic stem cells and characterized by the presence of primitive or atypical myeloid or lymphoid cells in the bone marrow and the blood. "Moreover, we found that some genes are also important for leukemia development (Jarid2, Metap2, Jak3, Pla2G15, Zfp384, Casp8 and Dpf2)." (PMID 37700325, 2023).
melanoma (1 paper, 2025). A malignant, usually aggressive tumor composed of atypical, neoplastic melanocytes. "However, we observed that many ZDHHC13-interacting proteins showed significant correlation with SMPD2 and PLA2G15 expression levels in human melanoma datasets." (PMID 41321310, 2025).
cancer (3 papers, 2020 to 2022). A tumor composed of atypical neoplastic, often pleomorphic cells that invade other tissues. "We found that 30 of these genes which included Nckap1l, Ncf1, Pla2g15, Unc93b1, Lrrc33, Rgs10, Gmfg, Rbm25, C3ar1, Ccdc88b, Fam105a, Gng11, Phc1, Rasa4, Dag1, Tyrobp, Tmsb4x, Cfp, Prkd1, Gp49a, Trem2, C1qc, Lyz2, Igfbp7, Rab30, Cxcl16, Egfl7, Ube2r2, Pltp, and Cfb, showed a relation with cancer." (PMID 32812032, 2020).
tumor (3 papers, 2015 to 2024). "PLA2G15 expression was slightly reduced in all the tumor cell lines, except BCPAP, and strongly reduced in KAT-18." (PMID 26431489, 2015).
PLA2G15 also shares sentences with these, for which no sentence is quoted: infection (4 papers); Alzheimer disease (1); breast carcinoma (1); gastric cancer (1); kidney (1); liver steatosis (1); lysosome disease (1); neurologic disease (1); neuropathy (1); Niemann-Pick disease type C (1); senile cataract (1); Sepsis (1); spinocerebellar ataxia (1); Splenomegaly (1); tuberculosis (1); uveitis (1); viral infection (1).